COA1 (cytochrome c oxidase assembly factor 1)
Description:
Component of the MITRAC (mitochondrial translation regulation assembly intermediate of cytochrome c oxidase complex) complex, that regulates cytochrome c oxidase assembly. MITRAC complexes regulate both translation of mitochondrial encoded components and assembly of nuclear-encoded components imported in mitochondrion. Required for assembly of mitochondrial respiratory chain complex I and complex IV. As part of the MCIA complex, required for efficient assembly of the mitochondrial complex I.
Synonyms: C7orf44; MITRAC15; FLJ10803
Tractability: Antibody: UniProt predicts a signal peptide or a membrane-spanning region. PROTAC: ubiquitination databases record sites on it.
Gene: Protein-coding gene on chromosome 7 (43,608,456 to 43,729,857, reverse strand). Ensembl gene ENSG00000106603.
Subcellular location: Mitochondrion inner membrane
Subcellular location (Human Protein Atlas): Mitochondria
Pathways (Reactome):
Metabolism: Complex I biogenesis; Complex IV assembly; Respiratory electron transport
Gene Ontology:
Molecular function: protein binding
Biological process: mitochondrial respiratory chain complex I assembly; mitochondrial respiratory chain complex IV assembly
Cellular component: mitochondrial complex I intermediate assembly complex; mitochondrial inner membrane; mitochondrion
Genetic constraint (gnomAD): Loss-of-function variants: 9 observed, 7.58 expected, observed/expected ratio (o/e) 1.19, 90% interval 0.71 to 1.84. That is too few expected variants to judge how well the gene tolerates losing a copy. Missense variants: 141 observed, 140.91 expected, observed/expected ratio (o/e) 1, 90% interval 0.87 to 1.15. Synonymous variants: 48 observed, 55.51 expected, observed/expected ratio (o/e) 0.86, 90% interval 0.69 to 1.1.
Homologues: Orthologues: chimpanzee COA1 (98% identical), macaque COA1 (92% identical), dog COA1 (51% identical), tropical clawed frog coa1 (40% identical), zebrafish coa1 (37% identical), Drosophila melanogaster CG15653 (25% identical), Drosophila melanogaster CG31913 (23% identical).
Diseases named in the same sentence as COA1 in open-access papers:
COA1 is named in the same sentence as 11 diseases in open-access papers, as found by Europe PMC text mining. Sharing a sentence is not in itself a finding about the gene and the disease. The quoted sentences say what the papers report.
colorectal cancer (2 papers, 2022). A primary or metastatic malignant neoplasm that affects the colon or rectum. "The microarray assay showed that overexpression of COA1 in colorectal cancer tissues is associated with poor prognosis, and suppression of COA1 expression reduces the growth of colorectal cancer cell lines." (PMID 35818360, 2022). "Although the cancer-based study of COA4, a mediator protein in the assembly process of the cytochrome c oxidase complex, is lacking, overexpression of its related protein (COA1) has also been shown in colorectal cancer." (PMID 35818360, 2022).
giant cell tumor (2 papers, 2020 to 2022). A benign, intermediate, or malignant tumor that arises from the bone or soft tissue. "In addition, miR-127 inhibited tumor growth via targeting cytochrome c oxidase assembly factor 1 homologue (COA1) and protein disulfide isomerase family A, member 6 (PDIA6) in giant cell tumor of bone." (PMID 32051829, 2020).
COVID-19 (1 paper, 2023). A disease caused by infection with severe acute respiratory syndrome coronavirus 2. "Among them, we can highlight the involvement of slc2a1a, slc2a1b (cell membrane glucose transport), interleukins- il1b, and il6 (pro-inflammatory pathway), nfkbiab, and coa1 (mitochondrial respiratory chain) in COVID-19." (PMID 37047078, 2023).
cancer (2 papers, 2019 to 2022). A tumor composed of atypical neoplastic, often pleomorphic cells that invade other tissues. "This unique metabolic profile leads to upregulation of certain enzymes and proteins such as ALDH1, CEP55, IDO COA1 etc., which can be utilized for development of vaccine based anti-cancer immunotherapy." (PMID 31106150, 2019).
COA1 also shares sentences with these, for which no sentence is quoted: tumor (3 papers); breast carcinoma (2); bone cancer (1); esophageal cancer (1); giant cell tumor of bone (1); glioma (1); melanoma (1).